IL6 (interleukin 6)
Diseases named in the same sentence as IL6 in open-access papers (continued):
Sharing a sentence is not in itself a finding about the gene and the disease.
liver fibrosis (continued). "RT-PCR analyses supported these observations by showing that mRNAs of inflammatory mediators, IL-1β, IL-6, MCP-1, MCP-3 and TIMP-1 increased in CCl4- and BDL-induced liver fibrosis, and decreased in BI 113823-treated mice." (PMID 36514072, 2022). "The decrease in pro-inflammatory cytokines (IL-6, IL-1β, and TNF-α) is accompanied by regression of liver fibrosis in CCl4-intoxicated rats." (PMID 35881285, 2022). "Inflammatory cytokines, such as TNF-α, IL-6, or MCP-1, led to the induction of NFkB that accelerates the progression of liver fibrosis." (PMID 35294499, 2022). "In liver fibrosis mice model, high selenium level elevated expression and activity of GPx and superoxide dismutase with decreasing level of MDA, TNF-α, IL-6 and MCP-1." (PMID 35975984, 2022). "Activation of proinflammatory cytokines and chemokines, including IL-6, IL-1β, TNFα, and MCP-1, can activate HSCs, promote ECM secretion and deposition, and then exacerbate liver fibrosis." (PMID 35525986, 2022). "We investigated the changes in cytokines, interferon gamma (IFN-γ), tumor necrosis factor-α (TNF-α), and interleukin 6 (IL-6) along with aspartate aminotransferase (AST), alanine aminotransferase (ALT) level, and hepatic fibrosis in three regimens." (PMID 35889747, 2022). "Accumulating evidence identifies a leading role of the IL-6 pathway in HSC activation, which is critical for the progression of liver fibrosis." (PMID 35907883, 2022). "Evodiamine was able to reduce IL-6, TNF-α, and types I and III collagen expression, inhibit the TGF-β1/Smads signaling pathway, and attenuate liver fibrosis." (PMID 35529927, 2022). "In this context, the authors indicated that IL-17 levels (as a part of other secreted ILs as IL-6, IL-10, IL-21, IL-1β and INF-γ) increased in CHC and its level correlated directly with the degree of liver fibrosis." (PMID 35056005, 2022). "Consistent with our previous study and the in vitro findings of the present study, we found that DIM significantly reduced the expression levels of IL-1β, IL-6, COX-2, iNOS, and TNF-α in CCl4-induced liver fibrosis." (PMID 36232707, 2022). "Our data on the effective reduction in M1 polarization markers NOS2, Il6, and TNF-α make siRNA to IRF5 a strong candidate for in vivo modulation of liver fibrosis." (PMID 36010574, 2022). "IL-6 was a good indicator of EHI, and MCP-1 was significantly positively correlated with HBV DNA but negatively correlated with liver fibrosis." (PMID 36389814, 2022). "Subsequently, the increase of proinflammatory mediators (i.e., TNF-α, IL-6, and IL-1β) and fibrogenesis markers (i.e., TGF-β1, α-SMA, and collagen I), as well as hepatic fibrosis in NASH stage two, were observed in the fructose group." (PMID 36359236, 2022). "The levels of pro-inflammatory cytokines (IL-1β, IL-6, and TNF-α) showed a significant (P < 0.05) increase after 5 and 9 weeks of hepatic fibrosis induction in rats compared with normal control rats." (PMID 35881285, 2022). "The results of the present study revealed that melatonin, IL-6, and TNF-α levels have a significant increasing trend with the progression of liver fibrosis." (PMID 34221262, 2021). "After that, the effective rate of treatment, the incidence of adverse reactions, liver function indexes, liver fibrosis condition, and TNF-α and IL-6 expression levels were all compared between the two groups." (PMID 34484339, 2021). "In a CCl4 model of liver fibrosis, the attenuation of fibrosis by sorafenib correlated with increased STAT3 phosphorylation in hepatocytes which was dependent on KC-derived IL-6." (PMID 34047814, 2021). "In addition, the effects of CVC on liver fibrosis are related to the reduction of inflammation-related biomarkers, such as IL-6, IL-1β, etc., which indicates that CVC is a great potential anti-liver fibrosis candidate drug because inflammation is one of the important factors causing liver fibrosis." (PMID 34621747, 2021).
liver fibrosis (continued). "These inflammatory factors contribute to the progression of liver fibrosis, while TNF-α can stimulate collagen synthesis and IL-6 and IL-1β can activate hepatic stellate cells and directly stimulate collagen secretion." (PMID 34899328, 2021). "Magnesium chenoursodeoxycholic acid (Mg-CUD) suppression increases MMP-2 and tissue inhibitor of MMP-1 mRNA expression, as well as levels of NF-κB, TNF-α, IL-6, and COX-2 in carbon tetrachloride-induced liver fibrosis in rats." (PMID 34220502, 2021). "It was concluded that IL-6/STAT3 signaling prevents cholestasis and liver fibrosis and has role in regulation of hepatocyte and cholangiocyte functions in the model of sclerosing cholangitis." (PMID 33841164, 2021). "Currently, some researchers believe that a combination of TFAs and fructose induces oxidative stress and increases TNFα, IL-6, IL-1β and collagen-Iα expression levels, which partly explained the roles of TFA and fructose in liver fibrosis progression." (PMID 32508961, 2020). "Impressively, this combination also remarkably inhibited the pre-inflammatory mediators release of IL-6 and TNF-α, which provides a specific target in the screening of anti-inflammatory drugs for the treatment of schistosomiasis-induced liver fibrosis." (PMID 33553120, 2020). "A series of studies from Ling's team suggested that 800 mg/kg dietary cyanidin-3-O-β-glucoside alleviated liver fibrosis by suppressing inflammatory factors, such as TNF-α, IL-6, and IL-10." (PMID 33082829, 2020). "In the present study, we identified a mixed profile of elevated circulating inflammatory cytokines, chemokines, and growth factors, including IL-6, IL-10, IFN-γ, GM-CSF, and FGF-basic, among HIV–HCV-coinfected patients with advanced liver fibrosis." (PMID 33348839, 2020). "Our results are also in agreement with literature data showing a role for JAK/STAT pathway in the modulation of liver fibrosis, as in the case of STAT3 activation in hepatic stellate cells treated with IL-6 and leptin." (PMID 31861914, 2019). "Knocking out dectin-1 exacerbated liver fibrosis and inflammation, as demonstrated by increased expression of TNF-α, IL-6, and MCP-1, neutrophil and macrophage influx, and fibrosis progression." (PMID 31717860, 2019). "The neutralization of Th17 cells attenuates liver fibrosis in BDL and CCl4 models through IL-17, IL-1b, TNF-α, IL-2, IL-6, TGF-β serum levels reduction, and downregulation of IL17A and the IL6/STAT3 signaling pathway." (PMID 31671842, 2019). "TNF-α also increases liver fibrosis by promoting activated HSCs to produce a large number of ECM proteins and to secrete several soluble cytokines, such as TGF-β, IL-1, IL-6, VEGF and ET-1." (PMID 28358817, 2017). "In the progression of liver fibrosis, activated Kupffer and HSC cells secrete large amounts of IL-6 and TGF-β1, promote the transformation from Treg to Th17, resulting in reduced secretion of IL-10 and increased secretion of IL-17." (PMID 28646179, 2017). "The recently published sequence of key events leading to liver fibrosis involve hepatocellular injury/death, KC-activation and macrophage recruitment, TGF-β1 expression and release of cytokines (TNF-α and IL6), HSC activation, and collagen accumulation." (PMID 28665955, 2017). "For example, plasma leptin, TNF-α and IL-6 levels positively correlate with hepatic injury and fibrosis deposition in WAT and the liver, while adiponectin attenuates hepatic fibrosis." (PMID 26891322, 2016). "Hepatic protein expression of Tnf-α and Il-6 was greater in recuperated offspring, suggesting that inflammation plays a role in the HSC activation and consequent hepatic fibrosis observed in our model." (PMID 26718412, 2016). "Anti-IL-9Ab treatment sharply decreased plasma concentrations of TGF-β1, IL-6, IL-4, and TNF-α in a mouse model of liver fibrosis." (PMID 26728971, 2016).
liver fibrosis (continued). "We further examined the role of the endogenous IL-9 in hepatic fibrosis and its relationship with other relevant cytokines, including IL-17A, IFN-γ, TGF-β1, IL-6, IL-4, IL-21 and TNF-α in response to hepatic fibrosis, by neutralizing IL-9 in a mouse model." (PMID 26728971, 2016). "Animal studies have demonstrated that chronic vitamin D deficiency or the deletion of Vdr−/− gene in mice lead to spontaneous development of liver fibrosis with abnormal increase in the levels of TGF-β1 and IL-6 as well as a significant decrease in IL-10." (PMID 27681697, 2016). "Out study showed that treatment with anti-IL-9Ab and anti-IL-17Ab exerted similar effects on suppressing plasma secretion and liver expression of TGF-β1, IL-6, TNF-α, IL-4 and IL-9 in mice with liver fibrosis." (PMID 26728971, 2016). "caused liver fibrosis whereas IL-17A can promote the activation of HSC and drive the mRNA expression of the IL-6, α-SMA, collagen, as well as TGF-β1 in carbon tetrachloride–induced liver fibrosis." (PMID 25649869, 2015). "Taken together, BBG reduces hepatic pro-inflammatory cytokines IL-6, TNF-α, PDGF, and IL-1β expressions, down-regulates TGF-β signaling pathway, and ameliorates liver fibrosis." (PMID 25933224, 2015). "Research indicated that the serum or plasma TNF-α and IL-6 levels was higher in NASH compared healthy subjects and it was shown to correlate with liver fibrosis in advanced NAFLD." (PMID 26375281, 2015). "Treatment with genistein decreased levels of inflammation mediators, including IL-6, TNF-α, and myeloperoxidase, through downregulation of NF-κB in alcohol- and CCl4-induced liver fibrosis in rats." (PMID 25897319, 2015). "On the other hand, IL-6 directly promotes HSC survival and proliferation during enhanced liver fibrosis." (PMID 25076488, 2014). "One approach utilizes the testing of biochemical markers of liver fibrosis: hyaluronic acid, adiponectin, high-sensitivity CRP, type IV collagen, serum IL-6, leptin, laminin, c-peptide, and cytokeratin-18." (PMID 23555578, 2013). "Increasing evidences have indicated the pivotal characters of various cytokines such as interleukin-6 (IL-6), TGF-β in the progression of hepatic fibrosis." (PMID 23840852, 2013). "Interleukin-6, hyaluronic acid, and the FIB-4 hepatic fibrosis index were higher among participants who developed progressive CKD, but were no longer associated with progressive CKD after adjustment." (PMID 22911697, 2012). "It is believed that both of these populations actively participate in development of liver fibrosis by secretion of TGF-β1, IL-6 and other profibrogenic cytokines." (PMID 22973518, 2012). "In a severe liver fibrosis model, treatment with cRLN2 not only effectively alleviated fibrosis but also restored the normal levels of inflammatory cytokine in serum (IFN-α, TNF-α, and IL-6)." (PMID 41552388, 2026). "Similarly, the 15 mg/kg dose exhibited greater efficacy, reducing IL-6 and IL-1β levels by 54.62% and 47.06%, respectively, and enhancing IL-10 levels by 227.27% as compared to TAA-induced liver fibrosis group." (PMID 41365955, 2025). "Among these inflammatory cytokines, IL-6, TNF, and TGF-β are key pro-inflammatory and pro-fibrotic factors that maintain immune responses, tissue repair, and homeostasis, and activate hematopoietic stem cells and drive liver fibrosis." (PMID 40778202, 2025). "As a result, several other cytokines, such as TGF-β, IL-22, IL-10, and IL-6, which are known to play important roles in liver fibrosis, were not covered, as they were not addressed in the eligible studies." (PMID 40362271, 2025). "D-Glucuronolactone, naturally abundant in animal livers, demonstrates hepatoprotective effects by enhancing the activity of antioxidant enzymes (SOD, GPx and GSH) and decreasing the production of inflammatory cytokines (IL-1β, IL-6 and TNF-α) in thioacetamide-induced liver fibrosis models." (PMID 41195363, 2025).
liver fibrosis (continued). "PAE was found to inhibit hepatic fibrosis by reducing activated HSC proliferation, migration, and the expression of collagen fiber genes COL1 and α-Sma, as well as inflammatory markers TNFα and IL-6, and EMT markers (ECA, NCA, Vim, Snail)." (PMID 40103586, 2025). "The initial investigation explored whether MO crude extract and OLA ameliorate hepatocyte injury and liver fibrosis on LX-2 cells by the analysis of cytokine and ECM production (IL-6, IL-8 and MMP-9)." (PMID 40244247, 2025). "IL-6 treatment was shown to prompt macrophages to release miR-223-rich exosomes, which subsequently reduced the expression of the fibrosis-promoting transcriptional coactivator with PDZ-binding motif (TAZ) in hepatocytes, thereby ameliorating liver fibrosis." (PMID 39995661, 2025). "Similarly, previous study showed that ertugliflozin treated groups at different concentrations significantly lowers IL-6 and TNF-a in liver fibrosis model." (PMID 41341617, 2025). "This study examined whether 3-HBI could reduce liver fibrosis in LX-2 cells by detecting its impact on the production of cytokines and the extracellular matrix (ECM) (IL-6, IL-8, and MMP-9)." (PMID 40649803, 2025). "However, a recent study revealed thatC. sinensis ESPs promoted the production of IL-6 in mouse BECs through the TLR2-mediated AKT and p38 pathways, resulting in the aggravation of hepatic fibrosis in mice." (PMID 39314046, 2024). "IL-6, TNF, and IL-1-β may act synergistically with TGF-β, and the genetic deletion of these cytokines may reduce the development of liver fibrosis." (PMID 39063116, 2024). "Its beneficial effect on hepatic fibrosis may be due to its inhibition of pro-inflammatory cytokines such as IL-6 and TNF-α in the liver; however, the other mechanisms involved in reducing hepatic fibrosis by EMPA remain unclear." (PMID 37962587, 2024). "Also, another study stated that pazopanib can halt rat liver fibrosis through modulating the pro-inflammatory cytokines TNF-α and IL-6." (PMID 37458952, 2023). "In bile duct ligation (BDL) mice, toxic bile acids further activate NLRP3 inflammasome assembly and cause Kupffer cells to develop the M1 phenotype, leading to the production of proinflammatory cytokines, including IL-6, TNF, and IL-1β, which aggravate liver fibrosis and damage." (PMID 36969233, 2023). "Moreover, MAMPs and bile acids from the intestine in PBC can promote Kupffer cells to exhibit the M1 phenotype, secrete IL-6, TNF, and IL-1β, and aggravate liver injury and liver fibrosis." (PMID 36969233, 2023). "Similarly, it has been recorded that vinpocetine efficiently reduced increased levels of hepatic IL-6, TNF-α, and TGF-β1, in a rat model of hepatic fibrosis." (PMID 36594060, 2023). "In addition, the upregulated release of proinflammatory (TNF-α and IL-6) and profibrogenic (TGF-β) cytokines by Kupffer cells and stimulated HSCs is one of the first manifestations of liver fibrosis." (PMID 36978885, 2023). "IL-6 through its receptors of IL-6R (CD236) and glycoprotein 130 can activate the Janus kinases (JAK) and signal transducer and activator of transcription 3 (STAT3) signaling, enhancing liver fibrosis." (PMID 37679346, 2023). "According to this study, DPx potently inhibited pro-inflammatory cytokines (IL-1, IL-6, and TNF-α), which may be key factors in preventing hepatic fibrosis." (PMID 37324954, 2023). "Furthermore, it was observed that the levels of Acta2, Col1a1, Col3a1, Tnfa, Il6, and Il1β genes were significantly increased upon STAT3 overexpression, again suggesting that STAT3 mitigated liver fibrosis." (PMID 36588728, 2022). "The histology results revealed that liver fibrosis was alleviated (with the recovery of parenchyma cells, reduced collagen deposition, and α-Sma expression) with reduced inflammation (decreased TGF-β1 and IL-6 expression)." (PMID 35933403, 2022).
liver fibrosis (continued). "Consistently, the mRNA levels of inflammatory mediators TNF-α and IL-1β, as well as IL-6, ICAM, CCL2, CXCL2, and TGF-β, which were indicated as progressive inflammatory response and liver fibrosis, were significantly elevated in the liver of MFG-E8 knockout mice compared with the MCD-WT group." (PMID 35769208, 2022). "In this study, we found that TRPM8 inhibition could reduce the F4/80 positive cell population and inhibit the transcript levels of IL-6, IL-1β, TNFα, and MCP-1 in murine models of liver fibrosis." (PMID 35525986, 2022). "Xiang and others reported that IL-6 can be regulated by Hepatic leukemia factor (HLF) transcription and enhance the phosphorylation of STAT3, thus activating primary hepatic stellate cells and then aggravating hepatic fibrosis." (PMID 35462928, 2022). "The global cytokine surveys of HSC-CM have demonstrated that TNF-α, agrin, PDGF, activin A, GM-CSF, IFN-γ, IL-1β, IL-4, IL-6, IL-10, IL-13, and TIMP-1, which subsequently induce acute inflammation and liver fibrosis, were elevated in aHSC-CM relative to the qHSC-CM." (PMID 36142683, 2022). "In cattle, liver fibrosis has been proposed as a downstream effect of upregulated TNF and IL1B, which would activate the genes that were also upregulated in the bovine study, i.e., IL6, PLAU, SERPINE1, TNFRSF1A, SOCS1, and CTSB." (PMID 34616397, 2021). "Our data showed that PHI had a good anti-inflammatory effect in mice with CCl4-induced liver fibrosis, which represented as the reduction of serum LPS, MIP-1 and TNF-α levels as well as the decreased expressions of three inflammatory factors (IL-1β, IL-6, and TNF-α) in liver tissue." (PMID 34621179, 2021). "In this study, LMF-HSFx induced-IL-6 and IFN-γ suppression may play a role to reverse liver fibrosis in NAFLD patients." (PMID 33809062, 2021). "Previous study reported that catalase, anti-IL-6, or siRNA-IL-6 inhibited the phosphorylation of p38 in Kupffer cells which co-cultured hepatic stellate cell and also blocked TIMP1 upregulation and collagen I accumulation for liver fibrosis." (PMID 33809062, 2021). "Finally, in order to explore the role of WEPE in the inflammatory response of liver fibrosis, we evaluated the levels of TNF-α, IL-1β, and IL-6 in the rat serum." (PMID 34712342, 2021). "The elevation in TNF-α, IL-6, NF-κB and TGF-β lead to liver fibrosis." (PMID 34969385, 2021). "Moreover, administration of IL-22 inhibits HSC activation, reduces the production of pro-inflammatory factors (IL-1β, IL-6, and TNF-α), and ameliorates liver fibrosis in CCl4-induced liver fibrosis." (PMID 33869241, 2021). "Expression of IL-6, IL-1β, and TNF-α was also decreased in the acute hepatic fibrosis model." (PMID 33262757, 2020). "Peng's research demonstrated that 70 mg/kg baicalin had a significant effect on CCl4-induced liver fibrosis, which was correlated with immunoregulation of the imbalance between profibrotic and anti-fibrotic cytokines, including TGF-β1, TNF-α, IL-6, and IL-10 expression." (PMID 33082829, 2020). "Indeed, knockout of TREM-1 (Triggering receptor expressed on myeloid cells), which is highly expressed on KCs in liver fibrosis, reduced liver fibrosis through the inhibition of TNF-α and IL-6 responses in a number of chronic injury models." (PMID 32612603, 2020). "The HLF/IL‐6/STAT3 feed forward circuit could induce the activation of HSCs, resulting in liver fibrosis." (PMID 32306539, 2020). "Thus, critical roles for IL-33 in activation of Th2 immune responses via cytokines IL-4, IL-6 and IL-13 have been demonstrated in the pathogenesis of HSEC proliferation and liver fibrosis in mouse models." (PMID 32486265, 2020). "In conclusion, irritative factors such as CCl4 injection stimulate the proliferation of M1 macrophages, which further trigger HSC activation into α-SMA-positive myofibroblasts to accelerate the development of liver fibrosis by expressing TNF-α, IFN-γ, and IL-6." (PMID 30635047, 2019).